DCPH1 (damage control phosphatase 1)
Description:
Metal-dependent phosphatase that shows phosphatase activity against several substrates, including fructose-1-phosphate and fructose-6-phosphate. Its preference for fructose-1-phosphate, a strong glycating agent that causes DNA damage rather than a canonical yeast metabolite, suggests a damage-control function in hexose phosphate metabolism. Has also been shown to have O-methyltransferase activity that methylates glutamate residues of target proteins to form gamma-glutamyl methyl ester residues. Possibly methylates PCNA, suggesting it is involved in the DNA damage response.
Synonyms: ARMT1; C6orf211; FLJ12910
Tractability: PROTAC: ubiquitination databases record sites on it.
Gene: Protein-coding gene on chromosome 6 (151,452,258 to 151,470,101, forward strand). Ensembl gene ENSG00000146476.
Subcellular location (Human Protein Atlas): Nuclear bodies; Cytosol; Nucleoplasm
Gene Ontology:
Molecular function: enzyme binding; fructose 6-phosphate aldolase activity; fructose-1-phosphatase activity; phosphatase activity; protein binding; protein carboxyl O-methyltransferase activity; S-adenosylmethionine-dependent methyltransferase activity
Biological process: DNA damage response
Genetic constraint (gnomAD): Loss-of-function variants: 13 observed, 19.08 expected, observed/expected ratio (o/e) 0.68, 90% interval 0.44 to 1.08. The upper end of that interval is the gene's LOEUF score, 1.08, which puts it in group 4 of 6, group 1 being the genes least tolerant of losing a copy. Missense variants: 349 observed, 382.03 expected, observed/expected ratio (o/e) 0.91, 90% interval 0.84 to 1. Synonymous variants: 129 observed, 138.37 expected, observed/expected ratio (o/e) 0.93, 90% interval 0.81 to 1.08.
Homologues: Orthologues: chimpanzee ARMT1 (99% identical), macaque ARMT1 (96% identical), dog ARMT1 (88% identical), rabbit ARMT1 (86% identical), pig ARMT1 (84% identical), guinea pig ARMT1 (83% identical), mouse Armt1 (77% identical), rat Armt1 (76% identical), tropical clawed frog armt1 (61% identical), zebrafish armt1 (57% identical), Caenorhabditis elegans F31D4.2 (35% identical), Drosophila melanogaster CG2921 (34% identical), and 3 more.
Diseases named in the same sentence as DCPH1 in open-access papers:
DCPH1 is named in the same sentence as 12 diseases in open-access papers, as found by Europe PMC text mining. Sharing a sentence is not in itself a finding about the gene and the disease.
DCPH1 shares sentences with these, for which no sentence is quoted: breast carcinoma (9 papers); tumor (3); cancer (1); chronic myeloid leukemia (1); colon cancer (1); Fibroadenoma (1); heart failure (1); Hypertension (1); invasive ductal carcinoma (1); leukemia (1); ovarian carcinoma (1); prostate carcinoma (1).